SOD1 (superoxide dismutase 1)
Diseases named in the same sentence as SOD1 in open-access papers (continued):
Sharing a sentence is not in itself a finding about the gene and the disease.
cancer (continued). "The second subnetwork containing 13 nodes and 12 edges showed the interaction between PRDX2 and TAGLN2 as well as a mild increase in multiple components of the peroxisome (SOD1, CAT, PRDX5, PRDX1) and proteoglycans in cancer (FLNA, STAT3)." (PMID 38322285, 2023). "Our results indicated NOTCH1, NOTCH3, FLCN, SOD1, SOD2, NF1, and TLR4 as upregulated proteins in different cancer types highlighting their role in cancer progression." (PMID 35001007, 2022). "In the clinic, tetrathiomolybdate (TTM) anions are used to chelate cupric cations and have been shown to potently inhibit SOD1, which uses cupric cations as a co-factor, leading to clinical trials of TTM as anti-cancer agents." (PMID 35732120, 2022). "S100A8 markedly induced expression of several redox genes on Day 10, including superoxide dismutase (SOD1) (5.8 x 105 fold, p < 0.01) and thioredoxin (TXN) (1.5 x 105 fold, p < 0.05) in lungs of mice with LLC cancers." (PMID 35655772, 2022). "In vitro studies also showed that the fast growth of non-small cell lung cancer (NSCLC) and leukemia depends on the high activity of SOD1, which controls the oncogenic KRAS and EGFR pathways, as well as other cancer cells and xenograft tumors." (PMID 35011380, 2021). "In cancer treatment, ATN-224-mediated SOD1 inhibition led to the downregulation of PDGF and increase of O2•−, prevented the formation of high levels of H2O2, and protected protein tyrosine phosphatases from oxidation by H2O2." (PMID 35011380, 2021). "To further evaluate the clinical significance of our findings, we examined SOD1 expression and its relationship with ribosome biogenesis in a human LUCA transcriptome dataset from The Cancer Genome Atlas (TCGA)." (PMID 33859191, 2021). "Cancer cells upregulate several copper chaperones such as the copper chaperone for SOD1 (CCS), which binds cytosolic copper and transfers it to SOD1." (PMID 34390123, 2021). "Proliferative capacity is essential for the growth and development of malignant tumors; therefore, we used the CCK-8 assay to test the effect of SOD1 on NSCLC cell proliferation." (PMID 32391354, 2020). "The uncontrollable growth of cancer cells is attributed to the intracellular sustained high levels of H2O2 provided by upregulated expression and activity of SOD1." (PMID 30911355, 2019). "The comparison of the average SOD1, SOD2, and SOD3 mRNA synthesis in normal and PTC showed 4.6% (SD 4.9), 3.5% (SD 17.1), and 18.6% (SD 13.1) decreased expression in cancer, respectively." (PMID 29478325, 2019). "The design of PNA, consisting of a novel combination of a HSA and nitroxide as a metal-free superoxide dismutase (SOD3) mimetic, has advantages over small molecular weight and membrane permeable nitroxide that mimics SOD1, SOD2, and SOD3, in cancer therapy." (PMID 30941174, 2019). "Our results suggest that inhibition of SOD1 by PTDC has potential clinical application as a single agent, or in combination with other known cancer therapeutics." (PMID 25996379, 2015). "Disulfiram (DSF), currently in clinical cancer trials is activated by copper chelation, being potentially capable of diminishing the copper dependent activation of MEK1/2 and SOD1/SOD3 and promoting reactive oxygen species (ROS) toxicity." (PMID 26356671, 2015). "In this study, to elucidate the abilities of PDTC-induced oxidative stress combined with ROS production, we investigated the effect of PDTC on the antioxidant gene SOD1, JNK activation and NF-κB inhibition in hematopoietic human cancer cells." (PMID 25996379, 2015). "Collectively, these data identify SOD1 as a novel candidate drug target in BLM and CHEK2 cancer contexts, and further suggest that 2ME2, ATTM and LCS-1 are lead therapeutic compounds warranting further pre-clinical study." (PMID 26318585, 2015). "SOD1 stayed at similar levels, SOD2 expression increased in cancer, and SOD3 mRNA synthesis decreased correlating to reduced differentiation degree of thyroid tissue." (PMID 26664298, 2015).
cancer (continued). "In addition to the development of neoplastic alterations in human gastrointestinal tissues, SOD1 and SOD2 also have a role in the progression of tumors in the following sequence: benign tumor—malignant tumor—metastasis." (PMID 40867576, 2025). "Specifically, two key enzymes—SOD1 and SOD2—protect cancer cells from oxidative damage." (PMID 40867576, 2025). "We also identified SOD1 and BACH1, involved in regulating cellular responses to oxidative stress, and transcription factor RUNX1 that can regulate cancer cell proliferation and metastasis." (PMID 40018643, 2025). "The tumor-suppressive action of SOD1 and the observation that mice lacking the SOD1 gene exhibit immediate cancer development highlight the intricate relationship between cancer and oxidative stress." (PMID 39199144, 2024). "Additionally, DDC‐mediated suppression of SOD1 further enhances SF sensitivity in HBV‐positive HCC cells and xenografted animals, thereby inhibiting cancer progression more effectively." (PMID 39034442, 2024). "Hence, SOD1 is an important means of regulating superoxide anion radical (O2–) and hydrogen peroxide (H2O2) levels in cancer cells." (PMID 37822927, 2023). "In a mouse model of oxidative stress (Sod1 KO mice), oxidative stress most significantly exacerbated cancer cachexia-induced muscle functional impairment, but not muscle mass loss, by disrupting neuromuscular junction." (PMID 37014882, 2023). "Our results showed that the depletion of CHI3L1 increased SOD1 expression in cancer cells but not in normal cells." (PMID 37215572, 2023). "Moreover, increasing evidence points to the importance of nuclear SOD1 in the pathogenesis of ALS and cancer." (PMID 35204309, 2022). "Therefore, CQ can effectively inhibit SOD1 at micromolar concentrations (IC50: 6.7~43.1 μM) and induce the death of a variety of cancer cells through the caspase-3-mediated apoptosis pathway." (PMID 35011380, 2021). "The regulation of SOD1 and SOD2 by the sample may affect the inflammation and cancer pathways, and some diseases have preventive and control effects." (PMID 34079813, 2021). "Because SOD1 is the major type of SOD located in the mitochondrial intermembrane space, its impairment might contribute to cancer tumorigenesis." (PMID 34203465, 2021). "Further, HuD regulates the expression of mRNAs involved in the pathogenesis of neurodegenerative diseases or cancer, including amyloid precursor protein (APP), β–site APP–cleaving enzyme 1 (BACE1), lncRNA BACE1AS, neprilysin (NEP), tau, superoxide dismutase 1 (SOD1), and MYCN." (PMID 33922479, 2021). "Through specific inhibition of SOD1 activity, LD100 can efficiently up-regulate the intracellular concentration of O2•−, down-regulate the concentration of H2O2, down-regulate the phosphorylation of ERK1/2, and finally induce the apoptosis of cancer cells." (PMID 35011380, 2021). "The localization and distribution of SOD1, NOS2, and COX2, revealed a widespread broadening in bronchiolar and alveolar cells, as well as in the metastatic masses, evidencing the pulmonary reaction to the cancer injury." (PMID 32423132, 2020). "We hence measured the levels of one of the most active cytosolic antioxidant enzymes involved in radical species detoxification, namely superoxide dismutase-1 (SOD-1), both in the two EOC cell lines and in human fibroblasts, to ascertain if indeed cancer cells expressed higher levels of the protein." (PMID 32085609, 2020). "The results showed that both mRNA and protein expression levels of SOD1 expression in cancer tissues were significantly higher than those in adjacent normal tissues." (PMID 32391354, 2020). "Resveratrol-induced SOD2 expression was observed in cancer cells, although the expression of SOD1, CAT and GPX1 was not affected." (PMID 32316674, 2020). "Probably a product of the SOD1, H2O2, is an important signaling molecule for cancer cells." (PMID 28280522, 2017).
cancer (continued). "Thus, superoxide dismutase (SOD1;TIF = 1.13, t-score = 5.04), which converts harmful superoxide radicals to hydrogen peroxide and oxygen, helps prevent DNA damage and is a possible cancer therapeutic target, and also impinges on the ALS pathway." (PMID 20187943, 2010). "Furthermore, overexpression of oxidative stress (SOD1, Ape1/Ref-1, Trx, and PDI) and DNA repair (MPG and Ape1/Ref-1) proteins has been shown to provide resistance to chemotherapeutic agents and impede cancer treatment." (PMID 20064251, 2010). "However, previous studies have described that MT1A, compared to SOD1, has low specificity; its expression is influenced by various pollutants, including cadmium, arsenic, copper, and PM10, as well as conditions like neoplasms and cancer." (PMID 41012407, 2025). "Results showed that the expression of GCLC, SOD1 and SLC7A11 in ML385 treatment groups significantly decreased compared to that of the control groups, and the reduced antioxidant capacity re-increased the oxidative stress levels, resulting in the slowing-down of cancer cell proliferation." (PMID 37682862, 2023). "Consequently, mice lacking both copies of the cytoplasmic superoxide dismutase 1 (SOD1) gene or having one copy deleted for the mitochondrial superoxide dismutase 2 (SOD2) gene exhibit noticeable oxidative harm and experience spontaneous cancer development." (PMID 37927596, 2023). "Downregulated in this experiment, SOD1 does not support oncogene-dependent proliferation, that happened when it is overexpressed and maintains ROS levels below a threshold that support the growth of cancer cells." (PMID 36500393, 2022). "However, data on effects of the simultaneous expression of CAT and SOD1 on cancer promotion are not available." (PMID 36552527, 2022). "Because METTL7B enhanced the expression of essential ROS-scavenging enzymes, SOD1, GPX4 and HMOX1 as well as their enzymatic activities, it is worthy to explore whether METTL7B could promote resistance to other anti-cancer reagents in addition to TKIs in the future." (PMID 35144642, 2022). "It must be noted that, although not statistically significant, a trend for an increase in SOD-1 levels in fibroblasts but not in cancer cells may be observed in response to RL treatment alone, with a similar fold increase as with PA-RL." (PMID 32085609, 2020). "Also, we have revealed that the deletion of Sod1 does not exacerbate cancer‐mediated contractile dysfunction, cancer‐mediated mitochondrial dysfunction, and cancer‐mediated ROS production." (PMID 32918528, 2020). "Here, we deepened the study on nine of them (ASS1, EIF4G1, GALNT7, GLUT1, IGF2BP3 (IMP3), ITGA4, RAN, SOD1, and THBS2) to ascertain whether they are truly mesothelial cancer driver genes (CDGs) or genes overexpressed in an adaptive response to the tumoral progression (“passenger genes”)." (PMID 32659970, 2020). "To further characterize the liquid-plasma-induced death of cancer cells via ROS or RNS, we determined whether a knockdown or overexpression of the enzymes scavenging reactive species (SOD1/SOD2 and catalase) influenced the liquid-plasma-induced death of cancer cells." (PMID 27364630, 2016). "Thus, it seems plausible that the increased SOD1 expression in DCIS and IBC may help reduce ROS accumulation and promote cancer cell survival." (PMID 20064251, 2010). "At the molecular level, significant upregulation of GPX4 and GSTA2 was observed in both cancer cell lines, whereas NFKB expression increased selectively in HT-29 cells, with no notable changes in CAT or SOD1 expression." (PMID 41745011, 2026).
cancer (continued). "Although SOD1 is overexpressed in various cancers, the clinical significance and functions of SOD1 in non-small cell lung cancer (NSCLC), particularly the epigenetic regulation of SOD1 in NSCLC carcinogenesis and progression have been less well investigated." (PMID 32391354, 2020). "Interestingly, downregulation of SOD1 failed to ameliorate the cytotoxicity of Asc/TETA to cancer cells; in contrast, overexpression of catalase effectively halted the cancer cell death induced by Asc/TETA." (PMID 28280522, 2017).
infection (460 papers, 2006 to 2026). The state of being infected such as from the introduction of a foreign agent such as serum, vaccine, antigenic substance or organism. "G and A alleles of SOD1 G7958A individually were associated with lower limbs and higher body part localizations of the infection, respectively." (PMID 28512644, 2017). "This additive model explains 7% of the population variance in resistance, with each sod1 B allele decreasing the odds of infection by 2.2 (95% CI: 1.58–2.99), and each RADres1 E allele decreasing the odds of infection by 1.8 (95% CI: 1.32–2.43)." (PMID 26372103, 2015). "PbA infection was associated with a significant decrease in brain mRNA levels of the anti-oxidant enzymes SOD-1 and catalase (day 0 vs. day 5)." (PMID 24603727, 2014). "The association between allelic variation at sod1 and resistance to infection varied substantially among genetic backgrounds." (PMID 22724037, 2012). "Collectively, these results indicate that depletion of endogenous SOD1 makes cells more susceptible to apoptosis during MP12 infection." (PMID 21655261, 2011). "The levels of SOD1 in patients with cutaneous leishmaniasis caused by L. amazonensis or L. braziliensis are increased and may serve as biomarkers of these infections." (PMID 31998662, 2019). "However, the strength of the association between sod1 genotype and resistance to infection depended on genetic background." (PMID 22724037, 2012). "Furthermore, SOD-1, previously associated with P. vivax malaria, displayed connectivity only in the groups of patients with symptomatic disease, especially in those individuals who died upon infection." (PMID 23433077, 2013). "Our data are consistent with those observed in ZIKV-infected neuronal and liver cells, in which catalase and SOD-1 levels decrease during infection, facilitating viral pathogenesis." (PMID 40572291, 2025). "Both GCLC and SOD-1 mRNA levels declined within 12 h of infection, reaching significantly reduced levels at 48 h (0.5-fold) and 72 h (0.49-fold), respectively, as compared to the control (p < 0.05)." (PMID 41294830, 2025). "The CMAP amplitude of hindlimb muscles from SOD1 G93A mice infected with AAV-NRIP or AAV-GFP was measured from 100 days of age (post-infection day 40) to 147 days of age (post-infection day 87)." (PMID 39044305, 2024). "Infection with L. amazonensis increases SOD1 expression in mouse peritoneal and human macrophage lineages in a PKR/Nrf2-dependent way." (PMID 37507911, 2023). "Animal studies using SOD1-G85R ALS mice demonstrated that sublethal CVB3 infection that mimics chronic infection leads to early onset and accelerated ALS-like motor dysfunction, and shortened lifespan." (PMID 35812094, 2022). "Overall data revealed alleviated levels of SOD2 gene and decreased expression of SOD1 gene in response to C. trachomatis-infection leading to production of oxidative stress and RSA." (PMID 36038649, 2022). "Transcripts for Nrf2, Sod1, Sod2, and Cat in placentae from E8.5 infections (i.e., E16.5) were all significantly elevated relative to placentae from mice infected at E6.5 (i.e., E15.5; p ≤ 0.01)." (PMID 35312688, 2022). "Sod1, A Cu/Zn superoxide dismutase gene, mutants halve oxalate production and appears down regulated during SlaGemV−1 infection." (PMID 36146699, 2022). "SOD1, SOD2, and Catalase expression were studied, finding SOD1 downregulation after 24 and 48 h of infection." (PMID 36358519, 2022). "Direct ATCV-1 infections of neuronal cell lines in the context of SOD1-G93A overexpression are currently under investigation to better understand if and how these viruses contribute to MND through a specific cell type." (PMID 35280283, 2022). "In a multivariate model testing influence of both status and day on these transcripts, holding day constant revealed a significant impact of infection was retained for Nrf2, Sod1, Sod2, Cat and Hmox1 (p ≤ 0.04)." (PMID 35312688, 2022).